ACSL4 (acyl-CoA synthetase long chain family member 4)
Diseases named in the same sentence as ACSL4 in open-access papers (continued):
Sharing a sentence is not in itself a finding about the gene and the disease.
Sepsis (27 papers, 2019 to 2026). Sepsis is defined as life-threatening organ dysfunction caused by a dysregulated host response to infection. "Collectively, these findings establish ACSL4 as a central mediator of ferroptosis in sepsis-associated pericytes, suggesting its potential as a diagnostic biomarker for infectious pathologies." (PMID 40264754, 2025). "In vivo experiments using pericyte-specific ACSL4 knockout mice showed marked reductions in pericyte loss and enhanced vascular barrier function following sepsis induction." (PMID 40264754, 2025). "Sepsis patients showed a large upregulation of the ferroptosis-associated gene ACSL4, as well as a considerable upregulation of NFIL3." (PMID 39097582, 2024). "ACSL4 (AUC = 0.7127) was associated with predicting sepsis mortality." (PMID 40264754, 2025). "In the study, the causal link between sepsis and ACSL4/MYL6 was further investigated." (PMID 39262873, 2024). "Finally, to investigate the relationship between genetic variants of MYL6 or ACSL4 and sepsis, Mendelian randomization (MR) analysis was applied." (PMID 39262873, 2024). "In CLP-induced sepsis-associated lung injury, lactate-driven H3K18 lactylation increases METTL3 expression, which in turn stabilizes ACSL4 mRNA via m6A methylation and YTHDC1 recognition, thereby promoting ferroptosis in alveolar epithelial cells." (PMID 41515964, 2025). "The expression level of ACSL4 in the Cur + Sep group was 38.6% ± 4.5%, significantly higher than in the Sham group (18.3% ± 3.4%) and significantly lower than in the Sepsis group (74.6% ± 6.5%) (p < 0.05)." (PMID 41140036, 2025). "Collectively, these findings indicate that ACSL4, GPX4, and PTGS2, along with IL-6, hold significant diagnostic and prognostic value in sepsis." (PMID 40264754, 2025). "The results confirmed that serum levels of ACSL4 and GPX4 possess high diagnostic and differential diagnostic values for sepsis, comparable to the SOFA score, CRP, and PCT, and superior to the APACHE II score and GCS score." (PMID 40264754, 2025). "The survival curve analysis revealed that sepsis patients with elevated serum levels of ACSL4, CL-11, and IL-6 above the respective cutoff values had significantly shorter survival times." (PMID 40264754, 2025). "Future larger studies that incorporate repeated measurements and focus on specific pathogens are necessary to further clarify the multifaceted pathophysiological mechanisms underlying ACSL4 and GPX4 in sepsis." (PMID 40264754, 2025). "Our study demonstrated that ferroptosis-related protein markers ACSL4 and GPX4 possess significant diagnostic and differential diagnostic value in sepsis, including the ability to predict 28-day mortality in our study cohort." (PMID 40264754, 2025). "The Venn diagram shows that a total of eight overlapping genes were discovered between ACSL4 co-expression genes and sepsis, including GK, CLEC4E, ACSL1, TGFBR3, ADAM9, AZI2, BCAT1, and CYP1B1." (PMID 39262873, 2024). "The mRNA levels of MYL6 and ACSL4 in the LPS group were increased in vitro and in vivo experiments of sepsis-induced ALI models." (PMID 39262873, 2024). "Consistent with previous research findings, our investigation demonstrated a substantial upregulation of ACSL4 mRNA in sepsis-induced ALI." (PMID 39262873, 2024). "Continuing our pursuit of understanding the molecular underpinnings behind WWP2’s regulation of sepsis-induced myocardial injury and cardiomyocytes ferroptosis, our focus turned to the pivotal enzyme acyl-CoA synthetase long-chain family member 4 (FACL4)." (PMID 38591063, 2024). "In the present study, we used ROC curve analysis to evaluate the potential diagnostic value of ACSL4 and MYL6 in sepsis." (PMID 39262873, 2024). "In this study, our analysis based on the GEO database found that NFIL3 expression was elevated in patients with sepsis and significantly positively correlated with ACSL4." (PMID 39097582, 2024).
Sepsis (continued). "In this study, we analyzed the GSE134347 dataset and found that the rhythm gene NFIL3 is highly expressed in sepsis patients, inducing ferroptosis in renal tubular cells through upregulation of ACSL4." (PMID 39097582, 2024). "Based on literature as well as inferences from co-expression analyses in other literature, ACSL1 and ACSL4 expression levels were significantly higher in fatal sepsis cases." (PMID 39262873, 2024). "For instance, previous study in our lab has illustrated that circEXOC5 exacerbates ferroptosis by modulating PTBP1/ACSL4 axis in sepsis-induced ALI." (PMID 38395749, 2024). "The observed reductions in nonheme iron content and alterations in ferroptosis-related proteins, particularly GPX4 and ACSL4, underscore the significant role of iron metabolism and ROS management in sepsis treatment strategies." (PMID 39857660, 2024). "CircEXOC5 binds to PTBP1 to promote ACSL4 mRNA stability, leading to ferroptosis in sepsis-induced acute lung injury." (PMID 37686142, 2023). "CircEXOC5 can directly bind to RNA-binding protein polypyrimidine tract binding protein 1 (PTBP1) to enhance ACSL4 mRNA stability, leading to ferroptosis in sepsis-induced acute lung injury." (PMID 37686142, 2023). "Conclusively, our results revealed that uridine inhibited the ferroptosis via activating Nrf2 pathway and suppressing ACSL4 expression in sepsis-induced ALI in vivo." (PMID 36982166, 2023). "Consistently, the levels of other ferroptosis-related proteins, namely, acyl-CoA synthetase long-chain family member 4, cyclooxygenase II, and 5-lipoxygenase, were correspondingly increased in patients with sepsis." (PMID 35902564, 2022). "Since another member of the ACSL family, ACSL4, was also among the candidates which passed our selection criteria it was decided to attempt to confirm differential expression across multiple sepsis datasets." (PMID 31681299, 2019). "Inferences drawn from both the literature (via indirect associations) and public transcriptome data (via correlation) point to the likely participation of ACSL1 and ACSL4, another family member, in inflammasome activation in neutrophils during sepsis." (PMID 31681299, 2019). "Our findings suggest that HK2 modulates ISGylation of ACSL4 in sepsis-induced microglial cells, indicating that therapeutic targeting of HK2 may constitute a promising strategy for SAE." (PMID 40086696, 2025). "ACSL4 and GPX4 have strong diagnostic and differential diagnostic value in sepsis, including the ability to predict 28-day mortality in sepsis patients, and may become new potential serum markers for the diagnostic and differential diagnostic of sepsis." (PMID 40264754, 2025). "In addition, this article reports for the first time on ACSL4 as a disulfidptosis-related gene involved in sepsis-induced acute lung injury." (PMID 39262873, 2024). "An inhibitor of mmu-miR-7212-5p enhances Hmox1 expression and mitigates ferroptosis by diminishing Acsl4 expression, suggesting that mmu-miR-7212-5p inhibitors may represent a promising clinical therapeutic target for sepsis-related AKI." (PMID 39839617, 2024). "Hence, the TF–miRNA coregulatory interactions composed of these genes were used to search the latent genetic regulation between ACSL4 and sepsis." (PMID 39262873, 2024). "Furthermore, our study showed for the first time that the mRNA levels of MYL6 increase in sepsis, consistent with ACSL4 results." (PMID 39262873, 2024). "To explore the mechanisms causing ferroptosis in SA-AKI, we first analyzed the GSE134347 dataset and found that the rhythm gene NFIL3, together with important contributor to ferroptosis ACSL4, was significantly highly expressed in sepsis patients compared to healthy controls." (PMID 39097582, 2024). "We identified two key disulfidptosis-related DEGs in sepsis: ACSL4 and MYL6." (PMID 39262873, 2024).
Sepsis (continued). "We have discovered and confirmed that the key genes ACSL4 and MYL6, which are linked to disulfidptosis in sepsis-induced acute lung injury, may be useful in the diagnosis and management of septic acute lung injury." (PMID 39262873, 2024). "All those research studies were prompted that ACSL4 may affect sepsis through the interconnection between genes." (PMID 39262873, 2024). "Finally, we designed a validation study to investigate the differential expression of MYL6 and ACSL4 in sepsis-induced acute lung injury." (PMID 39262873, 2024). "In addition, analysis of the GEO database showed that NFIL3 was highly expressed in sepsis patients and was highly correlated with the key molecule of ferroptosis, ACSL4." (PMID 39097582, 2024). "In summary, our study provided novel insight into the pathological mechanisms of sepsis-induced cardiomyopathy, and miR-130b-3p /ACSL4 and miR-130b-3p /AMPK/mTOR signaling may be considered the new targets for the treatment of septic cardiomyopathy." (PMID 37705752, 2023). "In LPS‐induced in vitro sepsis model, subsequent to extracellular histone H3 treatment, LPS‐induced ferroptosis of HUVECs was enhanced, as evidenced by a decline in Gpx4 and an increase in ACSL4." (PMID 36705411, 2023). "ACSL1 was considered as an indicator of severe sepsis, in addition to ACSL4." (PMID 34960652, 2021). "Furthermore, available clinical data indicate that levels of ACSL1 and ACSL4 induction was significantly higher in fatal cases of sepsis." (PMID 31681299, 2019). "Additionally, the rhythm gene nuclear factor, interleukin 3 regulated (NFIL3), which is highly expressed in sepsis patients and correlates with ACSL4, modulates ferroptosis and inflammation in SA-AKI by promoting ACSL4-dependent lipid peroxidation in renal tubular epithelial cells." (PMID 41250137, 2025). "Similarly, elevated ACSL4 and PTGS2 in ICU sepsis patients are associated with heightened IL-6, IL-8, procalcitonin, as well as high-sensitivity C-reactive protein, demonstrating strong diagnostic performance for sepsis along with its inflammatory complications." (PMID 41250137, 2025). "Previous studies suggested that ACSL4 and MYL6 co-expression genes were closely associated with inflammatory response, immunosuppression, cell function metabolism, and other aspects in the progression of sepsis, which was consistent with our conjecture and research." (PMID 39262873, 2024). "Similarly, higher ACSL4 is also discovered by other clinical data in fatal cases of sepsis." (PMID 36705411, 2023). "In this study, we detected the serum levels of ACSL4, GPX4, and PTGS2 in ICU sepsis patients, non-sepsis patients, and healthy individuals." (PMID 40264754, 2025). "Compared with the Sepsis group, the Cur + Sep group showed significantly lower Paller damage scores, reduced Scr, BUN, TNF‐α, IL‐1β, IL‐6, MDA, Fe2+ levels, and ACSL4 protein expression (all p < 0.05)." (PMID 41140036, 2025). "In sepsis and ALI characterized by ACSL4-dependent ferroptotic injury, anti-ferroptosis agents warrant consideration." (PMID 41515964, 2025). "To further investigate the potential relationship and the underlying mechanisms between key genes and sepsis, we acquired ACSL4 and MYL6 co-expression genes from the Coexpedia dataset and then intersected with 403 DEGs in sepsis." (PMID 39262873, 2024). "The expressions of ACSL4 and MYL6 mRNA in the GSE95233 dataset were significantly increased in the sepsis group compared with the control group (p < 0.001)." (PMID 39262873, 2024). "ACSL4 and MYL6 mRNA expressions were significantly upregulated in sepsis groups compared with control groups (p < 0.001)." (PMID 39262873, 2024). "What is noticeable is that the expression level of ACSL4, a key molecule in ferroptosis, was significantly and positively correlated with NFIL3 in sepsis patients." (PMID 39097582, 2024).
Sepsis (continued). "Western blot analysis of ferroptosis-related proteins revealed that sepsis altered the expression of 4-HNE, FTH1, GPX4, ACSL4, PTGS2, and SLC7A11, which was reversed by ghrelin and Fer-1, indicating their role in inhibiting ferroptosis." (PMID 39857660, 2024). "After identifying ACSL4 and MYL6 as the key genes between DEGs in sepsis and DRGs, we further explored the mRNA levels of two key genes in the GSE26378, GSE28750, and GSE65682 datasets separately." (PMID 39262873, 2024). "To investigate the potential role of disulfidptosis in sepsis-induced ALI, first we used GEO2R online analysis software to identify DEGs and then intersected with DRGs to obtain the key genes: ACSL4 and MYL6." (PMID 39262873, 2024). "In a mouse model of sepsis-induced myocardial injury, matrine protects the damaged myocardium by activating the PI3K/AKT pathway to upregulate GPX4 expression and downregulate ACSL4 expression to inhibit ferroptosis." (PMID 37954843, 2023). "Here, we demonstrated the critical role of miR-130b-3p in attenuating sepsis-induced cardiac dysfunction via the regulation of the AMPK/mTOR signaling pathways and directly targeting ACSL4 to suppress the ferroptosis in septic cardiomyopathy." (PMID 37705752, 2023). "The data showed that the iron content and the expression of the pro-ferroptotic protein ACSL4 increased, while the anti-ferroptotic protein GPX4 expression reduced during sepsis." (PMID 35370723, 2022). "Previous studies have shown that in sepsis-related acute lung injury (ALI), lactate induces ACSL4-dependent ferroptosis in alveolar epithelial cells through METTL3-mediated m6A modification via the H3K18la/METTL3/ACSL4 axis." (PMID 41461917, 2025). "Additionally, both in vivo and in vitro experiments confirmed that the mRNA levels of ACSL4 and MYL6 in sepsis-induced acute lung injury were consistent with the results of bioinformatics analysis." (PMID 39262873, 2024). "Both in vivo and in vitro results were consistent, indicating higher ACSL4 and MYL6 mRNA levels in LPS-induced septic mice and cells, suggesting that ACSL4 and MYL6 may be potential therapeutic targets for sepsis-induced ALI." (PMID 39262873, 2024). "Furthermore, the increase in ROS causes an increase in iron content and alterations in the proteins GPX4, ACSL4, and SLC7A11, recognizing the role of ferroptosis in sepsis-related brain degeneration." (PMID 39768830, 2024). "Additionally, how ACSL4 and MYL6 regulate the involvement of disulfidptosis in the occurrence of acute lung injury in sepsis is also our next research direction." (PMID 39262873, 2024). "In addition, uridine supplementation mitigated sepsis-induced ALI by inhibiting macrophage ferroptosis via activating Nrf2 pathway and inhibiting Acyl-CoA synthetase long-chain family member 4 (ACSL4) expression." (PMID 36982166, 2023). "In summary, we described the dysregulated uridine metabolism in sepsis-induced ALI for the first time and discovered that uridine supplementation could inhibit ferroptosis of macrophage via Nrf2 pathway and ACSL4 inhibition." (PMID 36982166, 2023). "In addition, both in vivo and in vitro results have shown that in LPS-induced septic mice and cells, much higher ACSL4 and MYL6 mRNA levels were displayed, suggesting ACSL4 and MYL6 may possess the capacity to influence sepsis by inflammation response and immune infiltration." (PMID 39262873, 2024). "Baseline serum levels of ACSL4, GPX4, PTGS2, CL-11, IL-6, IL-8, PCT, and hs-CRP significantly differed among sepsis, non-septic, and healthy individuals (all p-value < 0.01)." (PMID 40264754, 2025). "For differentiating sepsis from non-sepsis in ICU patients, IL-8, ACSL4, GPX4, CRP, PCT, NEU%, IL-6, and PTGS2(p-value =0.007) exhibited significant diagnostic value (all p-value <0.00001)." (PMID 40264754, 2025).
colon cancer (25 papers, 2010 to 2025). "It has previously been reported that ACSL4 expression is associated with the malignant phenotype in both liver and colon cancer and functions to modulate proliferation." (PMID 24155918, 2013). "Overexpression of ACSL4 is associated with the development of colon cancer." (PMID 35126480, 2022). "Chromophobe renal cell carcinoma, renal cell carcinoma, tubular cell carcinoma, lung adenocarcinoma, and lung squamous carcinoma showed lower ACSL4 expression, while cholangiocarcinoma, colon cancer, and hepatic cell carcinoma showed higher expression level." (PMID 34053456, 2021). "ACSL4 catalyzes the conversion of free arachidonic acid into arachidonic acid-CoA ester and reduces the arachidonic acid-induced apoptosis in colon cancer." (PMID 27171439, 2016). "Third, it has been reported that free AA induces apoptosis in colon cancer cells and overexpression of ACSL4 blocked AA-induced apoptosis." (PMID 24879802, 2014). "A colon cancer cell model demonstrated that pharmacological inhibitors of ACSL4 and COX-2 show an additive effect in reducing cell proliferation." (PMID 22808264, 2012). "Finally, high expression level of CYGB had the close correlation with key genes YAP1 and ACSL4 in ferroptosis pathway in colon cancer based on analysis from TCGA data." (PMID 33611811, 2021). "Moreover, a combination of classical non-steroideal anti-inflammatory drugs aimed at inhibiting COX-2 and Triacsin C targeting ACSL4 has shown a synergistic pro-apoptotic effect in the colon cancer cell line HT29." (PMID 21085606, 2010). "In colon cancer cells, a cooperative metabolic network comprising overexpression of the Acyl-CoA synthetases ACSL1, ACSL4 and the related enzyme SCD induces EMT and increases cellular migration and invasion." (PMID 34073989, 2021). "Previous reports have demonstrated that the simultaneous activation of the ACSL4 and COX-2 pathways results in a synergistic anti-apoptotic effect in colon cancer." (PMID 21085606, 2010). "For this purpose we generated human colon cancer stable cell lines overexpressing either ACSL1, ACSL4 or SCD (ACSL1 cells, ACSL4 cells, and SCD cells, respectively) or the three genes simultaneously (x3 cells), transducing the DLD-1 CRC cell line with specific lentiviruses." (PMID 26451612, 2015). "Collectively, these results imply that ACSL1, ACSL4 and SCD increased expression might act as a marker of poor prognosis which contributes to reduced disease free survival of colon cancer patients." (PMID 26451612, 2015). "However, ACSL4 also can promote cancer progression in HCC and colon cancer." (PMID 37193981, 2023). "Also, ACSL1 and ACSL4 overexpression increases migration and invasion in colon cancer cells but not proliferation and contribute to a non‐Warburg advantageous energetic status of invasive colon cancer cells." (PMID 33030783, 2020).